ZMYND11 (zinc finger MYND-type containing 11)
Diseases named in the same sentence as ZMYND11 in open-access papers (continued):
Sharing a sentence is not in itself a finding about the gene and the disease.
Dystonia (1 paper, 2025). An abnormally increased muscular tone that causes fixed abnormal postures. "Notably, our data support a role of pathogenic variants in CHD6, KLC1, NR4A2, and ZMYND11 in dystonia even without neurodevelopmental features, while the relevance of identified VUS in several candidate genes remains unclear." (PMID 40533913, 2025). "Screening our data for proposed dystonia candidate genes identified presumably pathogenic variants in CHD6, KCNN2, KLC1, NR4A2, and ZMYND11, but not in others, for example, ATP5F1B, ACBD6, CIZ1, SHQ1, and SPTBN1." (PMID 40533913, 2025).
microdeletion syndrome (1 paper, 2021). "Haploinsufficiency of ZMYND11 is believed to play the main role in chromosome 10p15.3 microdeletion syndrome, a condition characterized by ID/DD, particularly affecting speech, craniofacial dysmorphism, hypotonia and seizures." (PMID 34680908, 2021).
Neurodevelopmental delay (1 paper, 2025). "10p15.3 microdeletion syndrome is a rare genetic disorder characterized by the loss of ZMYND11 and DIP2C genes, resulting in a range of neurodevelopmental delays, dysmorphic features, and gastrointestinal (GI) symptoms." (PMID 39958070, 2025).
prostate adenocarcinoma (1 paper, 2024). "We subsequently verified the downregulation of ZMYND11 using data from The Cancer Genome Atlas prostate Adenocarcinoma (TCGA PRAD)." (PMID 39341825, 2024).
Sepsis (1 paper, 2022). Sepsis is defined as life-threatening organ dysfunction caused by a dysregulated host response to infection. "In this study, WGCNA and DiffCorr were employed to find out novel hub genes including ZNF366, ZMYND11, SVIP and UBE2H, and we proposed for the first time their causative factors during sepsis progression." (PMID 35401666, 2022).
thyroid cancer (1 paper, 2025). "In our study, while we have made significant progress in understanding the roles of ETS2 and ZMYND11 in thyroid cancer, we must acknowledge that our research has certain limitations." (PMID 40938895, 2025).
tumor (19 papers, 2016 to 2025). "Downregulation of ZMYND11 expression is also linked to more aggressive cancer progression in a number of tissues, suggesting that ZMYND11 also functions as a tumor suppressor gene." (PMID 41279818, 2025). "Collectively, these studies have uncovered multifaced function and associated mechanisms of Zmynd11 in tumor." (PMID 40281637, 2025). "Although it has been shown that Zmynd11 regulates RNA polymerase II elongation in tumor, we observed that Zmynd11 deficiency reduced the binding of RNA Polymerase II at Epha2 promoter in eNPCs and brain samples." (PMID 40281637, 2025). "It is notable as well that KMT2A and ZMYND11 play opposite and complementary roles in cancer, with ZMYND11 functioning as a tumor suppressor while gain-of-function mutations in KMT2A drive oncogenesis." (PMID 41279818, 2025). "We discovered that patients with lower mRNA expression of ZMYND11 exhibited an increased risk of postoperative biochemical relapse, tumor progression to metastasis, and a shorter overall survival time." (PMID 39341825, 2024). "BS69 (ZMYND11) is a multi-domain chromatin-associated repressor protein that suppresses transcription elongation, regulates pre-mRNA processing and has tumour suppressor function." (PMID 31283782, 2019). "The potential interaction between ETS1 and ZMYND11 in the context of THCA could provide a more complex regulatory mechanism underlying tumor progression." (PMID 40938895, 2025). "Previous studies have shown that ZMYND11 plays critical function as tumor suppressor, and decreased ZMYND11 promotes tumor cell growth and migration, which is correlated with poor outcomes and lower survival rate." (PMID 40281637, 2025). "A recent study showed that Zmynd11 exhibits tumor repressive function by interacting with arginine methyltransferase PRMT5 and prohibiting the formation of HNRNPA1-mediated stress granule." (PMID 40281637, 2025). "This study identified the cellular senescence gene ETS2 as a tumor suppressor in THCA, which interacts with ZMYND11 to regulate THCA tumor progression through the mTOR pathway, thereby inhibiting cell senescence." (PMID 40938895, 2025). "In cancer, ZMYND11 modulates gene expression related to the cell cycle, differentiation, and apoptosis, influencing tumor growth." (PMID 40938895, 2025). "BS69/ZMYND11, a specific reader for the modified form of H3.3K36me3, has been suggested as a potential tumour suppressor." (PMID 40987316, 2025). "In a human cell culture model, ZMYND11, a known tumor suppressor and reader of Lysine 36 trimethylation on H3.3 (H3.3K36me3), suppresses RNAPII elongation." (PMID 39589400, 2024). "Depletion of ZMYND11 promotes tumor cell growth, migration, and invasion in vitro, as well as tumor formation and metastasis in vivo." (PMID 39341825, 2024). "As a transcriptional co-suppressor of oncogenes, ZMYND11 is down-regulated in a variety of malignant tumors and exerts broad-spectrum tumor-suppressive effects." (PMID 39044157, 2024). "To gain comprehensive insight into the dysregulation of the epigenetic reader ZMYND11 in cancers, we initially examined the expression of ZMYND11 across various human tumor types and adjacent normal tissue samples." (PMID 39341825, 2024). "The results indicated that reduced ZMYND11 expression enhanced the ability of tumor cells to form organoids." (PMID 39341825, 2024). "Clinically, we observed a strong inverse correlation between ZMYND11 expression and key indicators of tumor aggressiveness, such as metastasis, advanced tumor stages, and poor patient prognosis." (PMID 39341825, 2024). "Mechanistically, we discover that ZMYND11 exhibits tumor suppressive roles by recognizing arginine-194-methylated HNRNPA1 dependent on its MYND domain, thereby retaining HNRNPA1 in the nucleus and preventing the formation of stress granules in the cytoplasm." (PMID 39341825, 2024). "We also assessed the effect of ZMYND11 knockdown on tumor growth in vivo in a xenograft mouse model." (PMID 39341825, 2024).
tumor (continued). "In the present study, we report that ZMYND11 plays a critical role in suppressing tumor cell proliferation, metabolism, and cancer progression through a noncanonical function." (PMID 39341825, 2024). "BS69 (ZMYND11) is an emerging tumor suppressor that was originally identified as the Adenovirus protein E1A and EBNA2-interacting protein." (PMID 26845565, 2016). "Here, we determined the crystal structure of the coiled-coil and MYND tandem domains of BS69/ZMYND11, a candidate tumor suppressor, in complex with an EBNA2 peptide containing a PXLXP motif." (PMID 26845565, 2016). "In addition, ZMYND11 was remarkably decreased in glioblastoma multiform (GBM) tissues, while exogenous Zmynd11 significantly reduced tumor cell proliferation and invasion, and promoted cell cycle arrest and apoptosis." (PMID 40281637, 2025). "Notably, ZMYND11 is crucial for repressing a transcriptional elongation essential for tumour cell growth." (PMID 40987316, 2025). "Understanding how ZMYND11 triggers apoptosis could provide deeper insights into its tumor-suppressive functions and offer new therapeutic avenues for targeting SGs and enhancing cancer cell vulnerability to stress-induced apoptosis." (PMID 39341825, 2024). "In addition, DCBLD2, CASP7, TSC22D1, ANXA7, PRKAR2A, ZMYND11, and PAK2 have been reported to be tightly linked to tumor malignancy in previous studies." (PMID 35513372, 2022). "In addition, we show that the bromodomain histone reader ZMYND11 is a SPOP substrate implicated downstream of SPOP in the opposing regulation of the ERG and AR pathway in the two tumor subtypes." (PMID 33531470, 2021). "Furthermore, stable overexpression of ZMYND11 inhibiting tumor growth and lung metastasis." (PMID 39341825, 2024). "In vivo, ETS2 overexpression reduced tumor growth and increased ETS2 and ZMYND11 expression in xenograft tumors." (PMID 40938895, 2025). "The results of this investigation underscore the significant regulatory roles of ETS2 and ZMYND11 in THCA and their impact on tumor progression." (PMID 40938895, 2025). "The proteins RACK7/ZMYND8 and BS69/ZMYND11 are cancer related; they are tumor suppressive or oncogenic with context dependency upon histologic origin." (PMID 36520265, 2022). "In addition, IHC staining was performed on xenograft tumor tissues to assess the expression of ETS2 and ZMYND11." (PMID 40938895, 2025). "Furthermore, ZMYND11 counteracts the HNRNPA1-driven increase in the PKM2/PKM1 ratio, thus mitigating the aggressive tumor phenotype promoted by PKM2." (PMID 39341825, 2024). "This noncanonical function of ZMYND11 furthers our understanding of its tumor-suppressive mechanisms and elucidates its interactions with oncogenic pathways, such as the HNRNPA1-PKM2 axis." (PMID 39341825, 2024). "There was a notable divergence in gene expression levels between neoplastic and neighboring tissues, with genes such as BRCA1, CHEK2, and IKBKE substantially amplified in tumor tissues, while genes such as ZMYND11, MAPK8, and RPS3 exhibited notable elevation in adjacent nontumor tissues." (PMID 41497799, 2025).
cancer (12 papers, 2013 to 2025). A tumor composed of atypical neoplastic, often pleomorphic cells that invade other tissues. "In addition, the loss of the H3K36 methyltransferase SETD2 in several cancers also results in impaired chromatin interactions by ZMYND11." (PMID 34298819, 2021). "This raises the possibility of a complementary role for SETD2 and ZMYND11 in antagonizing cancer development, forming a coordinated axis in which SETD2-catalyzed H3K36me3 promotes ZMYND11 recruitment and inhibits KMT2A." (PMID 41279818, 2025). "Zinc finger MYND-type containing 11 (ZMYND11) is notably recognized for reading the epigenetic marker H3.3K36me3; however, its broader functions and mechanisms of action in cancer remain underexplored." (PMID 39341825, 2024). "To uncover the molecular mechanisms through which ZMYND11 regulates cancer cell growth and metastasis, we aimed to identify new proteins interacting with ZMYND11." (PMID 39341825, 2024). "This dual functionality highlights ZMYND11 as a key regulator of cellular stress responses and metabolic reprogramming in cancer cells." (PMID 39341825, 2024). "Further analysis using FACS to separate GFP-positive circulating cancer cells from the blood showed a significantly higher number of circulating 22Rv1 cells with ZMYND11 knockdown compared to controls." (PMID 39341825, 2024). "The zinc finger MYND-type containing 11 (ZMYND11) gene plays a role in cancer and a recent transcriptome meta-analysis in young and older humans showed an inverted expression profile of this gene in resistance training." (PMID 37606455, 2023). "These interactions highlight the crucial role of ZMYND11 as an important tumor suppressor and demonstrate how the interplay in epigenetic modifications contribute to cancer development." (PMID 34298819, 2021). "Our data reflect the heterogeneity of tumors in the H3/IDH1 wildtype group while also identifying two novel pHGG epigenetic cancer drivers (ZMYND11 and EP300) in this group." (PMID 29084603, 2017). "It should be considered that ZMYND11’s important roles in neuronal development and in cancer may both be mediated through inhibition of KMT2A." (PMID 41279818, 2025). "Furthermore, we demonstrate that tumors with low ZMYND11 expression exhibit enhanced sensitive to inhibitors of the type II arginine methyltransferase PRMT5, highlighting a potential therapeutic avenue for targeting cancers with ZMYND11 dysregulation." (PMID 39341825, 2024). "This suggests that ZMYND11 could serve as a valuable biomarker for guiding clinical diagnostics and therapy in cancer, particularly when considering the use of PRMT5 inhibitors." (PMID 39341825, 2024). "Indeed, ZMYND11 depletion caused up-regulation of MYC, and enhanced proliferation in cancer cells and mutations of ZMYND11 were identified in several cancers." (PMID 27631103, 2016). "Importantly, many of the MYND-containing proteins are associated with cancer and other diseases (e.g. ZMYND10, ZMYND11/BS69, ETO (eight-twenty-one)/MTG (myeloid translocation gene) family members, DEAF1, and Suppressin." (PMID 23408894, 2013). "Moreover, with ongoing clinical trials of a PRMT5 inhibitor (NCT03614728), our results suggest that assessing ZMYND11 expression levels could enhance the therapeutic potential of PRMT5 inhibition in cancer patients with lower ZMYND11 expression." (PMID 39341825, 2024). "However, ZMYND11 is a significant contributor to cancer development." (PMID 34298819, 2021). "ZMYND11, also known as BS69 or BRAM1, plays an important role in chromatin remodeling, and its coding locus in chromosomes is a region often missing in malignant tumors." (PMID 39044157, 2024). "Other anomaly like copy number variation (CNV) of BS69/ZMYND11 and promoter hyper methylation of BLU/ZMYND10 has been noted in malignancies." (PMID 36520265, 2022).
cancer (continued). "Our findings clearly indicate that ZMYND11 plays a critical role in inhibiting HNRNPA1-mediated oncogenic activities, including PKM splicing and stress granule formation, both of which are crucial for cancer cell survival and proliferation." (PMID 39341825, 2024). "Collectively, these findings suggest that ZMYND11 interacts with HNRNPA1 via the MYND domain and can limit the cytoplasmic translocation of HNRNPA1 to stress granules in stressed cells, thereby increasing the apoptosis of cancer cells." (PMID 39341825, 2024). "Although ZMYND11 DDR functions are unknown, it appears to play a central role in cancer suppression." (PMID 27631103, 2016). "Consequently, we aimed to ascertain whether ZMYND11 influences the alternative splicing of PKM pre-mRNA and affects the function of cancer cells." (PMID 39341825, 2024). "This functional diversity raises the possibility that ZMYND11 may possess non-canonical functions, including unconventional activities and antagonism toward key oncoproteins, which could be crucial in inhibiting cancer progression." (PMID 39341825, 2024).
infection (5 papers, 2016 to 2019). The state of being infected such as from the introduction of a foreign agent such as serum, vaccine, antigenic substance or organism. "As expected, the expression of ZMYND11 showed a pattern opposite that of gga-miR-19a on the 4, 5, 11, and 12th days post-infection." (PMID 27683641, 2016). "Moreover, different virulence NDV strains infection resulted in a similar suppression of these two proteins expression, indicated that a virulence-independent regulation of RNF11 and ZMYND11 during NDV infection in vitro." (PMID 31507581, 2019).
neurodevelopmental disorder (5 papers, 2022 to 2026). A behavioral and cognitive disorder with onset during the developmental period that involves impaired or aberrant development of intellectual, motor, or social functions. "Zinc finger MYND-type containing 11 (ZMYND11)-related neurodevelopmental disorder is an autosomal dominant condition caused by pathogenic variants in ZMYND11." (PMID 41820311, 2026). "Like ZMYND11, the gene encoding KMT2A is mutated in a neurodevelopmental disorder, Wiedemann-Steiner Syndrome (WSS), and KMT2A is also frequently mutated in cancer." (PMID 41279818, 2025). "ZMYND11, known for its role in neurodevelopmental disorders, acts as a transcriptional co-repressor by interacting with histone modifications to regulate RNA polymerase II activity." (PMID 40896579, 2025). "Herein, we describe four patients with rare neurodevelopmental disorders (SON, ZMYND11, DNMT1 and YY1-related diseases), who received a genetic assignment only in the adulthood." (PMID 35172867, 2022).
psychiatric disorder (1 paper, 2025). A disorder characterized by behavioral and/or psychological abnormalities, often accompanied by physical symptoms.
ZMYND11 also shares sentences with these, for which no sentence is quoted: acute myeloid leukemia (3 papers); autism (3); 22q11.2 deletion syndrome (1); brain glioma (1); chondroblastoma (1); diabetes (1); Down syndrome (1); epilepsy (1); generalized dystonia (1); genetic disorder (1); giant cell tumor (1); hyperglycaemia (1); Insulin resistance (1); Larsen syndrome (1); leukemia (1); lung carcinoma (1); Marfan syndrome (1); mesothelioma (1); neurological disorders (1); ovarian carcinoma (1); papillary carcinoma (1); polyneuropathy (1); prediabetes (1); prostate tumor (1); renal carcinoma (1); renal clear cell carcinoma (1); spondyloepiphyseal dysplasia congenital (1); syndromic intellectual disability (1); Tremor (1).